CHRM2 (cholinergic receptor muscarinic 2)
Diseases named in the same sentence as CHRM2 in open-access papers:
CHRM2 is named in the same sentence as 70 diseases in open-access papers, as found by Europe PMC text mining. Sharing a sentence is not in itself a finding about the gene and the disease. The quoted sentences say what the papers report.
alcohol dependence (8 papers, 2005 to 2025). Physical and psychological dependence on alcohol. "Chrm2 is strongly implicated in memory and cognitive function, and mutations of this gene were shown to predispose carriers to alcohol dependence and affective disorders." (PMID 39653249, 2025). "For example, in humans, the CHRM2 gene predisposes to alcohol dependence, drug dependence, as well as affective disorders including major depressive disorder." (PMID 39653249, 2025). "Additional analyses in the COGA sample have suggested that CHRM2 is associated with a generally increased risk of externalizing disorders, including symptoms of alcohol dependence and drug dependence." (PMID 23584813, 2008). "Linkage analyses demonstrated that the region containing the CHRM2 gene contributed to electrophysiological differences as well as to the risk of alcohol dependence and major depression." (PMID 17373405, 2006). "The muscarinic receptor CHRM2 gene associated with alcohol dependence and major depressive syndrome in COGA is also in this region." (PMID 16451582, 2005). "We found significant linkage and association between brain oscillations and genes involved with inhibitory neural networks (e.g., GABRA2, CHRM2), including frontal networks that are deficient in individuals with alcohol dependence, impulsivity, and related disinhibitory disorders." (PMID 17982586, 2007). "Subsequent association studies both in the COGA sample and in an independent sample identified several SNPs in the CHRM2 gene that were associated with alcohol dependence, major depression, and comorbid alcoholism and depression, as well as with electrophysiologic measures." (PMID 17373405, 2006). "SNPs in CHRM2 have been found with comorbid alcohol dependence and depression and comorbid alcohol and drug dependence." (PMID 26259089, 2015).
major depressive disorder (8 papers, 2006 to 2025). An episode of depression lasting two or more weeks without an intervening episode of mania. "SNPs within the cholinergic receptor muscarinic-2 (CHRM2) gene have been associated with predisposition to alcohol and drug dependence and with the development of affective disorders, including major depressive disorder." (PMID 35625928, 2022). "CHRM2 gene has been associated with intelligence, personality traits, substance dependence and depression." (PMID 30090216, 2018). "Other neurotransmitter genes Gabrb2 and Chrm2 were also modulated across treatment groups and warrant further exploration as they are associated with depression related clinical conditions." (PMID 25165739, 2014). "The role of CHRM2 in depression-mania switch phenomenon in bipolar disorder patients and the mechanisms behind warrant further investigation." (PMID 35455731, 2022). "The strongest one was observed between DRD2 and the frequency of alcohol consumption (p = 2.88E−08), followed by associations between the same gene (DRD2) and SCZ (p = 1.55E−07), CYP2D6 and SCZ (p = 1.81E−06), CHRM2 and major depressive disorder (p = 2.56E−06)." (PMID 31628418, 2021).
depression (6 papers, 2006 to 2023). "It is important to note that PPARG and PPARA are involved in lipid and glucose metabolism, while CHRM2 has been linked with depressive disorder." (PMID 37106802, 2023). "CHRM2 has been associated with nicotine dependence, while SLC6A15 has been associated with depression disorders." (PMID 37298272, 2023).
Arrhythmia (4 papers, 2010 to 2021). Any cardiac rhythm other than the normal sinus rhythm. "CHRM2 encodes muscarinic acetylcholine receptor M2 such that the missense mutation (C722 G) identified in the CHRM2 triggers heart failure, arrhythmia, and sudden death in the patients with dilated cardiomyopathy." (PMID 34456633, 2021). "In summary, we screened potential targets of active ingredients of WXKL involved in the regulation of arrhythmia through TCMSP and confirmed that WXKL could shorten the QT interval and slow down the heart rate by downregulating SCN5A and ADRB2 and upregulating CHRM2 during MI." (PMID 32565909, 2020).
gastric cancer (3 papers, 2021 to 2025). A primary or metastatic malignant neoplasm involving the stomach. "CHRM2, which mediates various cellular responses, has been demonstrated to be a significant marker of cognitive flexibility and a potential therapeutic target for gastric cancer." (PMID 34133324, 2021). "Previous studies have found that CHRM2 is enriched in the PI3K-Akt signaling pathway and its methylation rate rises as a progression of gastric cancer." (PMID 36212450, 2022).
schizophrenia (3 papers, 2013 to 2023). A major psychotic disorder characterized by abnormalities in the perception or expression of reality. "These post-mortem studies have been supported by a neuroimaging study demonstrating a reduction in muscarinic receptor availability in unmedicated patients with schizophrenia Whereas, post-mortem, neuroimaging, and genetic association studies implicate CHRM2 in the pathophysiology of mood disorders." (PMID 23805071, 2013). "In schizophrenia, subjects with deficits in CHRM1 protein expression also show a reduction in cortical and subcortical binding of [3H]AF-DX 384, a CHRM2/CHRM4 selective radioligand." (PMID 23805071, 2013). "In the striatum, it has been reported that levels of [3H]pirenzepine binding but not CHRM1 or CHRM2 mRNA, were lower in people with schizophrenia compared to controls." (PMID 36909280, 2023). "In addition, changes in CHRM1, but not CHRM2/4, signaling has been reported in the DFPLC in people with schizophrenia." (PMID 36909280, 2023). "Following that hypothesis, we would expect to have found comparable changes in the expression of some genes in the cortex of patients with schizophrenia where we have shown lower levels of CHRM18 and no changes in levels of CHRM2, 39, or 48 compared to that in controls." (PMID 34521861, 2021).
Alzheimer disease (2 papers, 2018 to 2021). A progressive, neurodegenerative disease characterized by loss of function and death of nerve cells in several areas of the brain leading to loss of cognitive function such as memory and language. "Variation in CHRM2 predisposes to various neuropsychiatric diseases, and Alzheimer’s disease." (PMID 34450027, 2021). "The aim of this study was to investigate the association of the polymerphic variation in CHRM2 gene (rs6962027) and CHRM3 gene (rs7511970) in relation to early- and late-onset of Alzheimer’s disease." (PMID 30090216, 2018).
Hypertension (2 papers, 2021). The presence of chronic increased pressure in the systemic arterial system. "Certain genes involved in the pathogenesis of hypertension—Alb, Chrm2, Xirp1, Kcnq1, Slc5a7, Kcnh1, Ache, Crlf1 and Galr2— should also be studied." (PMID 34603037, 2021).
nicotine dependence (2 papers, 2020 to 2023). Physical and psychological dependence on nicotine. "CHRM2 has also been reported as a candidate gene for nicotinic addiction by modulating presynaptic auto-regulation in the cholinergic system." (PMID 33168785, 2020).
Parkinson disease (2 papers, 2022 to 2023). A progressive degenerative disorder of the central nervous system characterized by loss of dopamine producing neurons in the substantia nigra and the presence of Lewy bodies in the substantia nigra and locus coeruleus. "A variety of ADRs belonging to movement disorders (e.g., extrapyramidal disorder, Parkinsonism, and dyskinesia) were associated with several targets, including OPRK1 (9 drugs), CHRM2 (8 drugs), and ADRA1A (5 drugs)." (PMID 37468498, 2023). "CHRNA4, MAOB and CHRM2 are targets for the treatment of Parkinson’s disease." (PMID 35566179, 2022).
prostate carcinoma (2 papers, 2021 to 2022). A carcinoma that arises from epithelial cells of the prostate gland. "This review showed that muscarinic receptors, such as CHRM2, 3, 4, and 5, were altered in breast, stomach, lung, colon, liver, and prostate cancers." (PMID 35565451, 2022). "We speculated that CHRM2 might be a prognostic factor for prostate cancer." (PMID 34133324, 2021).
Achalasia (1 paper, 2016). A disorder of esophageal motility characterized by the inability of the lower esophageal sphincter to relax during swallowing and by inadequate or lacking peristalsis in the lower half of the body of the esophagus. "We observed a number of sequences involving the calcium signaling pathway (ie, CACNA1C, CACNB2, KCNMA1, CHRM2, CAV1, and NCS1) that were differentially expressed and were able to characterize these genes into possible functions related to achalasia pathogenesis." (PMID 27511445, 2016).
allergic asthma (1 paper, 2011). A asthma with a basis in a pathological type I hypersensitivity reaction. "RYR2, CHRM2 and TNS3 polymorphysms were confirmed as associated with allergic asthma onset risk in an independent pediatric population." (PMID 21359210, 2011).
Anxiety (1 paper, 2021). Intense feelings of nervousness, tension, or panic often arise in response to interpersonal stresses. "CHRNA4 also impacts arousal, anxiety, and memory, and CHRM2, is important in learning, memory and higher order brain functions." (PMID 33897478, 2021).
bipolar disorder (1 paper, 2022). A disorder of the brain that causes unusual shifts in mood, energy, activity levels and the ability to carry out day-to-day tasks. "Positron emission tomography studies have reported a decrease in the CHRM2 selective agonist [18F]FP-TZTP in the anterior cingulate cortex of individuals with bipolar disorder." (PMID 35455731, 2022).
delirium (1 paper, 2025). A disorder characterized by confusion; inattentiveness; disorientation; illusions; hallucinations; agitation; and in some instances autonomic nervous system overactivity. "Polymorphisms in the CHRM2 gene were associated with different cardiovascular responses to induction doses of propofol, and independently with differences in postoperative delirium rates." (PMID 40136457, 2025).
delirium tremens (1 paper, 2021). "Only in an Asian candidate gene study an association between the CHRM2 gene (rs1824024) and the development of delirium tremens, which is the severe form of alcohol withdrawal, was also shown." (PMID 34674705, 2021).
endometrial cancer (1 paper, 2022). Primary or metastatic malignant neoplasm involving the endometrium (mucous membrane that lines the endometrial cavity). "Compared with the CHRM2 low expression group, the CHRM2 highly-expressed group contained upregulation of tumor-promoting pathways including endometrial cancer, Wnt signaling pathway, and estrogen signaling pathway." (PMID 36212450, 2022). "Further, CHRM2, GRIN1, L1CAM, and SEMA4F were found to be significantly associated with clinical stage, immune infiltration, immune response, and important signaling pathways in endometrial cancer." (PMID 36212450, 2022). "For the first time, our findings reveal that CHRM2 and GRIN1 play significant roles in endometrial cancer and are positively related to endometrial cancer prognosis." (PMID 36212450, 2022).
fibroid tumors (1 paper, 2021). "However, expression of CHRM2 is co-regulated with the expression of DRD2 in healthy myometrium but not in fibroid tumors, where correlation between these two genes has not been observed." (PMID 34440356, 2021).
injury (1 paper, 2025). Damage inflicted on the body as the direct or indirect result of an external force, with or without disruption of structural continuity. "In the SNL model, REST in DRG neurons not only facilitates the transition from acute to chronic pain following nerve injury but also contributes to the inhibition of Chrm2 and the reduction of muscarinic analgesia." (PMID 40093024, 2025).
lymphoid cancer (1 paper, 2024). "While cell lines from certain tissues seem to be equally inhibited by top GPCR drugs (e.g., lung), others are sensitive to specific GPCR drugs, such as lymphoid cancer cells, which are particularly inhibited by DRD2, CHRM1, CHRM2, HTR1A, and HTR2A antagonists." (PMID 38723607, 2024).
memory impairment (1 paper, 2021). "The reduction in total muscarinic cholinergic binding, cholinergic receptor muscarinic 2 (Chrm2) gene and choline acetyltransferase (ChAT) expression in different brain regions also correlates with transient spatial learning and memory impairment in JEV-infected rats." (PMID 33401749, 2021).
mood disorder (1 paper, 2022). A cognitive disorder a disturbance in which the person's mood is hypothesized to be the main underlying feature. "The CHRM2, one of the muscarinic receptors, involves the cholinergic system and plays an important role in the pathophysiology of mood disorders." (PMID 35455731, 2022).
myocardial ischemia (1 paper, 2024). A disorder of cardiac function caused by insufficient blood flow to the muscle tissue of the heart. "Furthermore, the action of WXKL may reduce the QT interval and dawdle the heart rate by downregulating sodium channel protein type 5 subunit alpha (SCN5A) and the beta-2 adrenergic receptor (ADRB2) and upregulating muscarinic acetylcholine receptor M2 (CHRM2) during myocardial ischemia." (PMID 39204108, 2024).
myopia (1 paper, 2025). "Drugs that block CHRM2 also slowed myopia progression in mice, and this effect was accompanied by a decrease in TGM2 expression." (PMID 40657400, 2025).
non-small cell lung carcinoma (1 paper, 2022). A group of at least three distinct histological types of lung cancer, including non-small cell squamous cell carcinoma, adenocarcinoma, and large cell carcinoma. "CHRM2 inhibits the invasion and migration of non-small cell lung cancer through the M2R/ERK/Akt/NF-κB axis." (PMID 36212450, 2022).
overactive bladder (1 paper, 2024). Symptom of overactive detrusor muscle of the urinary bladder that contracts with abnormally high frequency and urgency. "The observed upregulation of Chrm2 and Trpv2 detected in the bladder following VCR treatment seems to be aligned with this notion as these genes have been described to play a role in bladder contractility and overactive bladder pathology." (PMID 38951167, 2024).
primary hypertension (1 paper, 2022). "Among them, AGTR1, AKT1 with puerarin, EDNRA with tanshinone IIA, MAPK14 with daidzein, MAPK8 with ursolic acid, and CHRM2 with cryptotanshinone all have a strong correlation with GJD in the treatment of primary hypertension." (PMID 36046450, 2022). "The research uncovered that the key active ingredients of GJD in managing primary hypertension are puerarin, tanshinone IIA, daidzein, ursolic acid, and cryptotanshinone, which are mainly expected to contain a regulatory function in conjunction with AGTR1, AKT1, EDNRA, MAPK14, MAPK8, and CHRM2." (PMID 36046450, 2022).
primary immunodeficiency (1 paper, 2021). "In particular, we detected that ZAP70 was enriched in primary immunodeficiency, TNFRSF4, and CXCL5 were enriched in cytokine-cytokine receptor interaction, CTSG was enriched in the renin-angiotensin system, and the CHRM2 and CTSG were enriched in neuroactive ligand-receptor interaction." (PMID 34133324, 2021).
pulmonary disease (1 paper, 2020). "Although, CHRM2 is known to activate several signaling pathways in the nervous system, and little is known about the effect of this gene in pulmonary disease." (PMID 33168785, 2020).
viral myocarditis (1 paper, 2021). Myocarditis that is caused by an infection with a viral agent. "Subsequently, we learned intermolecular interactions of herbal components and their targeting heart-tissue-specific CHRM2, FABP3, TNNC1, TNNI3, TNNT2, and SCN5A and cardiac-myocytes-specific IL6, MMP1, and PLAT coupled with viral myocarditis." (PMID 34456633, 2021).
cancer (7 papers, 2014 to 2025). A tumor composed of atypical neoplastic, often pleomorphic cells that invade other tissues. "From the differential genes involved in these pathways, we identified several gene clusters uniquely upregulated in the CAFWPOI 4-5 type; neuronal development and function-related (RELN, MYH10, CACNB4, OXTR, CAV3, CHRM2) and inflammation and cancer-related (RELN, IL21R, EDNRB, CAV3, OXTR)." (PMID 36045118, 2022). "By combining the mutational data in the Catalogue of Somatic Mutations in Cancer (COSMIC) and the spatial information in the Protein Data Bank (PDB), SpacePAC is able to identify novel mutation clusters in many proteins such as FGFR3 and CHRM2." (PMID 24990767, 2014). "Comparing muscarinic receptor subtype expression levels in adenocarcinoma vs. normal colon samples, we consistently observed reduced CHRM1, CHRM2, and CHRM4 and increased CHRM3 RNA levels (log2fc normal relative to cancer tissue)." (PMID 35370785, 2022).
tumor (6 papers, 2021 to 2025). "First, gene-level differential analysis of the stromal component of KIRC against the other eight tumor types revealed 941 differentially expressed (DE) genes (q< 0.05, BH adjusted), including the Mcf2l, Exoc3l2, Olfr558, and Chrm2 listed as the top-ranked genes." (PMID 35079698, 2021). "The findings imply that the genes CHRM2, GRIN1, L1CAM, and SEMA4F in EC have pro- or oncogenic effects as a result of the combined activity of several signaling pathways influencing tumor growth." (PMID 36212450, 2022). "Key pathways activated in neoplasias by BAs are regulated by nuclear receptors, FXR, CAR, SHP, PXR, LXR and VDR and other membrane receptors such as S1PR2, TGR5, CHRM2 and CHRM3." (PMID 35429253, 2022). "Furthermore, tumor macrophages stimulated angiogenesis via activation of CHRM1 and CHRM2, which triggered the arginine metabolic pathway." (PMID 41516199, 2025).
lip (1 paper, 2025). "Novel loci include those mapping to LHX8 and TSBP1 (combined clefts), ARHGEF18 and ARHGEF19 (cleft lip with/without palate), FBN2 (cleft lip only), SLC35B3 (cleft palate only), CASC20 (Pierre Robin Sequence) and CHRM2 (non-syndromic cleft palate only)." (PMID 41075272, 2025).
nervous system disease (1 paper, 2023). "One disease also matches different targets; for example, nervous system disease can involve CYP19A1, TRPM8, CHRM2, etc." (PMID 37701374, 2023).
CHRM2 also shares sentences with these, for which no sentence is quoted: cardiomyopathy (2 papers); cardiovascular diseases (2); COVID-19 (2); drug dependence (2); dysautonomia (2); heart failure (2); insomnia (2); pancreatic cancer (2); adenocarcinoma (1); alcoholism (1); autoimmune disease (1); cholangiocarcinoma (1); cholestasis (1); cleft lip (1); Cognitive impairment (1); colorectal cancer (1); dilated cardiomyopathy (1); Dyskinesia (1); endothelial dysfunction (1); epilepsy (1); Graves disease (1); heart disease (1); ileitis (1); invasive carcinoma (1); learning disorders (1); leukemia (1); liver fibrosis (1); movement disorder (1); Parkinsonism (1); pneumonia (1).
A further 5 diseases each share a sentence with CHRM2 in 1 paper.